DMAC2 (distal membrane arm assembly component 2)
Description:
Required for the assembly of the mitochondrial NADH:ubiquinone oxidoreductase complex (complex I). Involved in the assembly of the distal region of complex I.
Synonyms: ATP5SL; FLJ10241
Tractability: No criterion of Open Targets' tractability assessment is met for any kind of drug.
Gene: Protein-coding gene on chromosome 19 (41,431,318 to 41,440,717, reverse strand). Ensembl gene ENSG00000105341.
Subcellular location: Mitochondrion
Subcellular location (Human Protein Atlas): Mitochondria
Pathways (Reactome):
Metabolism: Complex I biogenesis
Gene Ontology:
Biological process: mitochondrial respiratory chain complex I assembly
Cellular component: mitochondrion
Genetic constraint (gnomAD): Loss-of-function variants: 33 observed, 33.45 expected, observed/expected ratio (o/e) 0.99, 90% interval 0.75 to 1.32. The upper end of that interval is the gene's LOEUF score, 1.32, which puts it in group 5 of 6, group 1 being the genes least tolerant of losing a copy. Missense variants: 319 observed, 353.44 expected, observed/expected ratio (o/e) 0.9, 90% interval 0.82 to 0.99. Synonymous variants: 133 observed, 140.75 expected, observed/expected ratio (o/e) 0.94, 90% interval 0.82 to 1.09.
Homologues: Orthologues: macaque DMAC2 (88% identical), macaque DMAC2 (85% identical), dog DMAC2 (70% identical), pig DMAC2 (70% identical), mouse Dmac2 (67% identical), rat Dmac2 (65% identical), chimpanzee DMAC2 (63% identical), guinea pig DMAC2 (62% identical), rabbit DMAC2 (56% identical), zebrafish dmac2 (35% identical), Caenorhabditis elegans Y53G8AR.8 (28% identical), Drosophila melanogaster CG4042 (27% identical).